ZNF407-AS1 (ZNF407 antisense RNA 1)
Synonyms: LINC00909
Gene: Long non-coding RNA gene on chromosome 18 (74,582,514 to 74,598,885, reverse strand). Ensembl gene ENSG00000264247.
Diseases named in the same sentence as ZNF407-AS1 in open-access papers:
ZNF407-AS1 is named in the same sentence as 12 diseases in open-access papers, as found by Europe PMC text mining. Sharing a sentence is not in itself a finding about the gene and the disease.
ZNF407-AS1 shares sentences with these, for which no sentence is quoted: tumor (5 papers); cancer (3); glioma (3); ovarian carcinoma (2); acute myeloid leukemia (1); adrenocortical carcinoma (1); bladder urothelial carcinoma (1); clear-cell ovarian carcinomas (1); gastric cancer (1); pancreatic cancer (1); pancreatic ductal adenocarcinoma (1); serous ovarian carcinoma (1).